IGF1 (insulin like growth factor 1)
Diseases named in the same sentence as IGF1 in open-access papers (continued):
Sharing a sentence is not in itself a finding about the gene and the disease.
tumor (continued). "This suggests that increased intratumoral levels of IGF-1 may counter the favorable effects of tumor-lymphocyte infiltrates on patients’ OS." (PMID 28928360, 2017). "When tumor carriers were treated with emodin or rhein, skeletal-muscle IGF-1 was normal." (PMID 29152137, 2017). "Additionally, in the SA group, SSTR2 expression was positively correlated with the reduction of IGF-1 and tumor volume." (PMID 28396686, 2017). "The reduction of GH, IGF-1, and tumor size after treatment with SSA for 3 months was measured." (PMID 28396686, 2017). "Furthermore, we found that human IL-15 mediated insulin-like growth factor-1 production in CD215+ myeloid cells and blocking IGF-1 reduced the tumor-promoting effect of IL-15." (PMID 29255466, 2017). "Thus, it is possible that serum levels of IGF-1 are dependent on the type of tumour, as well as the local release ratio of IGF-1." (PMID 28143425, 2017). "In addition, IGF-1 expression was also weaker in NPC tumour tissues compared to adjacent normal tissues." (PMID 28143425, 2017). "Targeting the IGF-1 axis has already been shown promising anti-tumour effects in the clinics." (PMID 29281661, 2017). "Finally, miR-143 inhibited tumor growth and increased sensitivity of PC to docetaxel and IGF-1 treatment in vivo." (PMID 29291019, 2017). "In contrast, spontaneous neoplasia occurs in prostate epithelium from Igf1 transgenic mice." (PMID 27661006, 2017). "In addition, IGF-1 protein was detected in 6 of the 16 NPC tumour tissues (37.5%) and in 14 of the 16 tumour-adjacent normal tissues (87.5%) with varied IGF-1 immunoreactivity." (PMID 28143425, 2017). "The fact that insulin receptor signalling can stimulate protein synthesis and inhibit apoptosis and the fact that IGF-1 receptor signalling enhances cell proliferation explain how hyperinsulinaemia and increased IGF-1 may result in tumour growth." (PMID 27795741, 2016). "EphA4‐KO mice with IGF1 administration showed significant tumor weight gain to almost the WT level." (PMID 26923183, 2016). "Additionally, a significant correlation between the degree of tumor resection and the endocrinological outcome was observed (r = 0.598), serum levels of GH and IGF-1 continuing to grow in the presence of a tumor residue." (PMID 27453753, 2016). "Somatostatin analogues may also act indirectly by inhibiting the release of growth factors and trophic hormones (such as IGF-1 and insulin), or through inhibition of angiogenesis, which limits tumor growth." (PMID 26290466, 2016). "Indeed, we found that IGF-1 was involved in the intrinsic tumorigenic potential of metastatic tumor cells." (PMID 27764776, 2016). "The extent of decrease in IGF-1 levels during treatment may be the best predictor of tumor volume reduction, followed by age and degree of GH decrease, although tumor volume reduction does not always correlate with the degree of biochemical control." (PMID 26290466, 2016). "Therapeutic strategies aim to minimize tumor mass and normalize GH and IGF-1 levels." (PMID 26290466, 2016). "Additionally a significant correlation was observed between the degree of tumor resection and the endocrinological outcome (r = 0.598), therefore serum levels of GH and IGF-1 serum continued to grow in the presence of a tumor residue." (PMID 27453753, 2016). "A better understanding and re‐evaluation of the main role of IGF1 in regulating tumor progression could further enhance our cognition of the tumor development niche." (PMID 26923183, 2016). "Significant tumor weight gain was identified in the IGF1 injected EphA4‐KO tumor‐bearing mice." (PMID 26923183, 2016).
tumor (continued). "While IGF1 treatment could enhance tumor growth, it was unable to maintain IGF1 concentration in the blood at the WT level of an endogenous IGF1." (PMID 26923183, 2016). "However, tumor expression of IGF1 mRNA in HCC was reported to be significantly increased compared with adjacent non-tumor tissue." (PMID 27102295, 2016). "Thus, in addition to modulating GH release, GHRH indirectly regulates the proliferation of cells in multiple other tissues including tumor cells through a GHRH/GH/IGF-1 axis." (PMID 27774107, 2016). "Interestingly, however, data on tumor dimensions and comorbidities were less predictable based on GH and IGF-1 and on pre-selected stage of the disease." (PMID 26377024, 2016). "IGF-1, through the activation of key signaling pathways, enhancing the expression of pro-survival factors, such as Bcl2, Bcl-X(L) and Survivin, and favoring DNA damage repair, is a key target for enhancing the response of tumor cells to drugs." (PMID 27764776, 2016). "This is consistent with a number of studies that showed that by reducing tumor mass and, therefore, decreasing basal GH secretion, subsequent control of GH and IGF-1 levels with somatostatin analogues may be improved." (PMID 26519143, 2016). "The results showed that the EphA4‐deleted host could inhibit primary tumor growth and tumor metastasis mainly by decreasing the amount of IGF1 synthesis in the circulation and locally tissues." (PMID 26923183, 2016). "FFPE tissue samples from 184 (74 %) of 250 patients were available for analysis of IGF-1 pathway polymorphisms (preferentially tumor-negative tissue)." (PMID 26738606, 2016). "A review of data from published studies of all the somatostatin analogues suggested that tumor volume reduction is progressive with prolonged treatment, and that decreased IGF-1 levels are the best predictor of tumor volume reduction, followed by age and degree of GH decrease." (PMID 26290466, 2016). "Nevertheless we can confirm 6 of their identified genes (SPP1, TOP2A, AREG, EGR1, CD34, and IGF1) as well as one of the identified miRNAs (hsa-miR-101), that they found to be differentially expressed in lymph node metastases compared to primary tumours and to normal tissue." (PMID 26537449, 2015). "X10 as well as IGF1 significantly decreased tumor latency time." (PMID 25848982, 2015). "Furthermore, we identified insulin-like growth factor 1 (IGF-1) as a novel and direct target of miR-26a and revealed that miR-26a exerted its tumor-suppressor function, at least in part, by inhibiting IGF-1 expression." (PMID 27468358, 2015). "Furthermore, IGF1 has been shown to be involved in resistance to cytotoxic chemotherapy by several drugs and on a variety of tumor types, mainly through an anti-apoptotic effect, as we have found in the current work." (PMID 26329608, 2015). "They hypothesized that engaging the IGF-1/IGF-1R system enabled tumor cells to escape anti-EGFR-mediated treatment as a consequence of IGF-1-driven stimulation of the PI3K–Akt pathway." (PMID 26528439, 2015). "Also very well known is the effect of caloric restriction (which dramatically reduces IGF1 and enhances insulin sensitivity) on reducing the incidence of spontaneous and chemically-induced tumours in rodents." (PMID 26284118, 2015). "A cocktail of well characterized tumor growth factors (EGF, HGF, and IGF-1) were analyzed in parallel as a positive control to determine whether freshly-isolated tumor cells were able to respond to growth factor activation ex vivo." (PMID 25807104, 2015). "Because IGF-1 stimulation attenuated the anti-proliferative effects of metformin, we speculated that metformin and CP might have additive anti-tumor effects." (PMID 26287334, 2015). "However, the relationship of IGF1 levels in serum and tumor tissue and of its receptor levels with HCC growth and prognosis are very complex." (PMID 26329608, 2015). "In vivo findings also indicate a tumor-promoting role of IGF-1." (PMID 25743390, 2015).
tumor (continued). "A detailed protein expression analysis showed that tumours induced by AspB10 or IGF1 have a distinct expression pattern compared to tumours from insulin- or vehicle-treated mice; both the PI3K and the MAPK were found to be significantly upregulated after AspB10 and IGF1 treatment." (PMID 26242987, 2015). "Therefore, PAPPA appears as a better therapeutic target for HCC with more tumor specificity and less risks of side effects as compared to other IGF1 axis components." (PMID 26020769, 2015). "Moreover, we revealed that insulin-like growth factor 1 (IGF-1) is a target of miR-26a, and miR-26a exerted its tumor-suppressor function, at least in part, by inhibiting IGF-1 expression." (PMID 27468358, 2015). "However, tumor cells harboring activating mutations in PI3K were found to be resistant to caloric restriction, despite the reduction in insulin and IGF-1 levels." (PMID 26192445, 2015). "Since AKT inhibitor and ERK1/2 inhibitor also abolish the IGF-1 signaling, for anti-ER drug-resistant tumor with an elevated AGR2 level, our study also indicated that targeting IGF-1/AGR2 pathway might be a treatment strategy." (PMID 25956506, 2015). "Mouse models have indicated that IGF-1 may play a key role in tumor reduction via the AKT/mTOR pathway following caloric restriction." (PMID 25743390, 2015). "The IGF-1 system may also interact with components of the extracellular matrix (ECM) affecting tumor growth and progression." (PMID 25743390, 2015). "The limitations of this study include its retrospective nature and the lack of tumor biology data such as gene mutation and expression as well as laboratory data regarding serum IGF1, insulin, and adipocyte-derived leptin levels." (PMID 26684001, 2015). "In addition, miR-486 was shown to have a potent tumor suppressor role in NSCLC through direct targeting of IGF-1R as well as IGF-1." (PMID 25628647, 2014). "Thus, we can conclude that the better survival outcomes of patients with high preoperative serum IGF-1 were derived from better tumor prognosis." (PMID 24586785, 2014). "Additionally, IGF-1 has been shown to synergize with tissue hypoxia to enhance tumor growth and metastasis." (PMID 24595361, 2014). "Additionally, IGF-1 can stimulate tumor angiogenesis by increasing vascular endothelial growth factor (VEGF) levels." (PMID 25069390, 2014). "IGF-1 acts as a procarcinogen by enhancing tumour cell proliferation and decreasing cell death." (PMID 25402501, 2014). "How TLRs might be controlled by other events occurring during tumor development is illustrated by the regulation of TLR9 by insulin growth factor 1 (IGF1)." (PMID 25411122, 2014). "Indeed, by blocking osteoclasts, ZOL inhibits the release of growth factor (TGF-β, IGF-1...) trapped in bone matrix and liberated during bone resorption to activate proliferation of tumor cells." (PMID 25138053, 2014). "Growth hormone and IGF-1 have both well known proliferative and anti-apoptotic effects and their hypersecretion may theoretically induce tumor development and stimulate its growth." (PMID 25127456, 2014). "Next, we correlated the expression of IGF-1 to that of miR-190b in the 29 HCC tumor tissues and identified a marginally reverse correlation (P = 0.057), implying that miR-190b dysregulation might be associated with the decline of IGF-1." (PMID 24586785, 2014). "This study demonstrates that miR-486 functions as tumor suppressor by targeting IGF-1 in NSCLC." (PMID 25628647, 2014). "In the human RCC cell lines Caki-2 (from a primary tumor) and SK-RC-52 (from a metastasis), IGF-1 may enhance transforming growth factor-β (TGF-β) signaling and raise IGFBP-3 levels with TGF-β acting in synergy." (PMID 25069390, 2014). "Alternatively, ECM degradation can result in the release of IGF-1, which could directly promote tumor cell resistance to proapototic signals." (PMID 24885595, 2014). "However, IGF1 messenger expression is lower in human chirrotic tissues than in both tumour and normal liver tissues." (PMID 25225571, 2014).
tumor (continued). "In our current study we have investigated IGF-1 regulation of Cyr61 and whether targeting IGF-1 could inhibit Cyr61 induced tumor growth and proliferation." (PMID 25062088, 2014). "In patients who do not achieve biochemical control of the disease but have documented partial response to SRLs (>50 % reduction of GH and IGF-1 vs. baseline and/or tumor shrinkage >20 %) either switching to Pegvisomant monotherapy or combination therapy Pegvisomant + SRL should be considered (DR)." (PMID 25245336, 2014). "IGF-1 is critical to activate and sustain an inflammatory response in the liver, which is needed for hepatic metastasis, not only through direct, paracrine effects on tumor cell growth, but also through indirect effects involving the tumor microenvironment." (PMID 23426399, 2013). "For instance, the direct involvement in tumor progression and metastasis has been demonstrated for insulin-like growth factor 1 (IGF-1) and its receptor (IGF-1R), transforming growth factor β (TGF-β), vascular endothelial growth factor C (VEGF-C), and matrix metalloproteinases (MMPs)." (PMID 23409034, 2013). "Treatment with IGF-1 therefore resulted in exposure for longer time than treatment with HI and X10, which could explain the increase in tumor growth following treatment with IGF-1 in vivo." (PMID 24260289, 2013). "The investigators suggested that vitamin D may act by inhibiting the tumor growth-stimulating effects of IGF-1." (PMID 23442740, 2013). "Tumor AKT activation directly correlated with plasma IGF-1 levels." (PMID 23823800, 2013). "Treatment of DIO-mice with HI, X10 and IGF-1 also activates the PI3K pathway in MC38 cell allografts and after treatment with X10 and IGF-1 for 14 days, growth of the tumor allografts was significantly increased ≈ 1.5-fold and ≈ 2-fold, respectively, compared to control." (PMID 24260289, 2013). "Comparatively, the efficacy of pegvisomant ranged from about 75 to 97 %, octreotide from about 65 to 79 %, and lanreotide from about 50 to 76 % for a variety of efficacy measures including, but not limited to, reducing serum GH, normalizing IGF-1, and reducing tumor size." (PMID 23054327, 2013). "Chronically elevated insulin facilitates in tumour tissues increased activation of mitogenic, anabolic, and prosurvival pathways with the increased levels of insulin and concomitant elevated insulin-like growth factor 1 (IGF-1)." (PMID 23573093, 2013). "During bone resorption, other potentially tumor-stimulating growth factors such as transforming growth factorbeta (TGF-beta) and insulin-like growth-factor-1 are released by osteoblasts, facilitating tumor cell growth and proliferation, and attracting other tumor cells." (PMID 26237143, 2013). "Thus, complete removal of the tumour, normalisation of the GH secretion and the IGF-1 concentration, as well as preservation of pituitary function, are generally aimed at." (PMID 22550484, 2012). "Reduced activity in an IGF system might be associated with tumour progression and poor response to treatment, high expression levels of IGF-IR, IR, and IGF-I mRNAs with increased survival, and high circulating IGF-1 levels with a low risk of progression." (PMID 23226965, 2012). "In this study we found that TGFβ, while it did enhance pII cell invasion, it did so at a relatively high dose as compared with EGF and IGF-1, suggesting that at least its role in tumor invasion and metastasis is subsidiary to its effect as a growth inhibitory agent." (PMID 22860018, 2012). "The IGF1-mediated activation of IGF1R has been demonstrated to contribute to tumor progression." (PMID 22792137, 2012). "Both tumours have a peak incidence at puberty, and OS occur in an area of a high bone growth rate at long bone metaphyses, suggesting a role of growth hormone and IGF-1." (PMID 23226965, 2012).
tumor (continued). "The greatest effect in decreasing tumor progression was observed when starvation was combined with the TMZ treatment for two consecutive treatment cycles, which was associated with reduced serum glucose and IGF-1 levels." (PMID 22984531, 2012). "Similarly, the GH or IGF-1 response to SRL as a prognostic factor for successful tumour shrinkage has been controversial." (PMID 22550484, 2012). "Notably some previously defined oncogenic miRNAs (103/107, 1826, 191, 93) show significant increases in expression while known tumor suppressive miRNAs (15b, 98, 195, 200b, let-7c and let-7g) are significantly repressed with IGF-1 treatment." (PMID 23226206, 2012). "IGF-1 is a promoter of tumor cell growth in vitro, and it may expose colonic and rectal cells to a proliferative stimulus." (PMID 22449145, 2012). "Interestingly, the array data demonstrate that IGF-1 negatively alters levels of the tumor suppressor let-7 (let-7c, let-7g, and miR-98) and miR-16 (miR-195 and miR-15b) family members." (PMID 23226206, 2012). "Hence, it can be assumed that, at least in part, CR modulation of IGF-1 mediates its anti-tumor and anti-aging effects." (PMID 22934068, 2012). "Rapamycin has been shown to potently inhibit IGF-1-stimulated proliferation of tumor cells." (PMID 21197468, 2011). "We show that both naïve and tumor-educated primary lung macrophages stimulate the proliferation of lung epithelial cells in vitro; recombinant IGF-1 recapitulates this effect, and the degree of macrophage-induced growth stimulation correlates with media IGF-1 levels." (PMID 21699731, 2011). "Even after normalizing to total BALF protein levels, BALF IGF-1 was significantly higher in tumor-bearing animals than naïve controls (1.81 ± 0.33 vs. 0.95 ± 0.36 pg IGF-1/ug BALF protein, respectively, P < 0.01, mean ± SD), suggesting that more IGF-1 is produced in the lungs of tumor-bearing mice." (PMID 21699731, 2011). "CR induced inhibition of IGF-1/Akt signaling was recently demonstrated in CT-2A tumor and therefore could be a plausible mechanism of inhibiting NF-κB activation." (PMID 21479220, 2011). "A third IPA network represents the interaction between the tumour-promotingfactors IGF1, PDGF BB and CYR61.Although the expression of PDGF is constant in all cellpopulations, its receptor (PDGFR) is higher in H-PCA and Metacell populations compared to adjacent cells." (PMID 21479216, 2011). "The lungs of tumor-bearing mice contained 3.5-times more IGF-1 than naïve littermates, and media conditioned by freshly isolated tumor-educated macrophages contained more IGF-1 than media conditioned by naïve macrophages; IL-4 stimulated IGF-1 production by both macrophage subsets." (PMID 21699731, 2011). "The destabilized tumor vasculature that we observed upon cyclopamine treatment first lead us to speculate that we might observe a reduction in stromal Ang-1 and IGF-1, factors known to be regulated by Hh pathway." (PMID 20098680, 2010). "However, VEGF-A concentrations tended to be higher in patients with PR positive tumours (p = 0.069), and IGF-1 higher in ER/PR positive tumours (p = 0.075/0.074)." (PMID 20932344, 2010). "Host-derived Ang-1 and IGF-1 mRNA levels were downregulated by cyclopamine in the tumor xenografts." (PMID 20098680, 2010). "Microarray and bioinformatics analysis suggested that overexpression of AKR1C3 in PC-3 cells modulates estrogen and androgen metabolism, activates insulin-like growth factor (IGF)-1 and Akt signaling pathways, as well as promotes tumor angiogenesis and aggressiveness." (PMID 21134280, 2010).